IFNA13 (interferon alpha 13)
Description:
Produced by macrophages, IFN-alpha have antiviral activities. Interferon stimulates the production of two enzymes: a protein kinase and an oligoadenylate synthetase.
Target class: Secreted protein
Gene: Protein-coding gene on chromosome 9 (21,367,372 to 21,368,057, reverse strand). Ensembl gene ENSG00000233816.
Subcellular location: Secreted
Pathways (Reactome):
Hemostasis: Factors involved in megakaryocyte development and platelet production
Immune System: TRAF6 mediated IRF7 activation
Gene Ontology:
Molecular function: cytokine receptor binding
Biological process: defense response
Cellular component: extracellular region
Genetic constraint (gnomAD): Loss-of-function variants: 0 observed, 0.23 expected, observed/expected ratio (o/e) 0, 90% interval 0 to 1.87. That is too few expected variants to judge how well the gene tolerates losing a copy. Missense variants: 120 observed, 151.6 expected, observed/expected ratio (o/e) 0.79, 90% interval 0.68 to 0.92. Synonymous variants: 50 observed, 56.59 expected, observed/expected ratio (o/e) 0.88, 90% interval 0.7 to 1.12.
Homologues: Orthologues: macaque IFNA13 (95% identical), pig IFN-ALPHA-15 (67% identical), pig IFN-ALPHA-8 (67% identical), pig IFN-ALPHA-9 (67% identical), pig IFN-ALPHA-13 (66% identical), pig IFNA1 (65% identical), mouse Ifna9 (65% identical), pig IFN-ALPHA-4 (64% identical), mouse Ifna1 (63% identical), mouse Ifna13 (63% identical), mouse Ifna16 (63% identical), mouse Ifna6 (63% identical), and 31 more. Paralogues in human: IFNA1 (99% identical), IFNA6 (85% identical), IFNA5 (84% identical), IFNA14 (82% identical), IFNA2 (82% identical), IFNA21 (81% identical), IFNA4 (80% identical), IFNA10 (79% identical), IFNA17 (79% identical), IFNA8 (77% identical), IFNA16 (77% identical), IFNA7 (76% identical), and 4 more.
Diseases named in the same sentence as IFNA13 in open-access papers:
IFNA13 is named in the same sentence as 9 diseases in open-access papers, as found by Europe PMC text mining. Sharing a sentence is not in itself a finding about the gene and the disease. The quoted sentences say what the papers report.
Insulin resistance (2 papers, 2019 to 2025). Increased resistance towards insulin, that is, diminished effectiveness of insulin in reducing blood glucose levels. "For example, maternal Omega-3 PUFA intake during pregnancy affects offspring DNA methylation, influencing genes like MSTN, IFNA13, ATP8B3, and GABBR2, which are linked to insulin resistance, adiposity, and immune responses." (PMID 40507105, 2025). "Genes such as MSTN, IFNA13, ATP8B3, and GABBR2 showed methylation changes, potentially influencing insulin resistance, adiposity, and innate immune response in offspring." (PMID 40507105, 2025).
breast carcinoma (1 paper, 2021). "NKX2-3 and IFNA13 showed low expression levels in normal breast tissues, however, were highly expressed in breast cancer tissues." (PMID 34457116, 2021). "A multivariate Cox regression model was employed to establish a predictive model containing 6 characteristic genes (HEY1, IFNA13, NKX2-3, NR2F1, POU5F1, and YY1) correlated with the prognosis of breast cancer." (PMID 34457116, 2021). "Expression of the six BCPRS genes (IFNA13, HEY1, NKX2-3, NR2F1, POU5F1, and YY1) in breast cancer tissues was analyzed using Tabula Muris's FACS and droplet methods." (PMID 34457116, 2021). "In summary, BCPRS and BCPRS-related genes (HEY1, IFNA13, NKX2-3, NR2F1, POU5F1, and YY1) can be used to evaluate the immune microenvironment and tumor purity in breast cancer patients." (PMID 34457116, 2021). "The low expression level of POU5F1 and YY1 and high expression level of HEY1, IFNA13, NKX2-3, and NR2F1 were significantly related to poor prognosis in breast cancer." (PMID 34457116, 2021). "Therefore, a neural network-based model was constructed to predict cell types in breast cancer tissues based on genes YY1, POU5F1, NKX2-3, NR2F1, HEY1, and IFNA13." (PMID 34457116, 2021). "Furthermore, neural network-based deep learning models were established to predict breast cancer cell types using BCPRS-related genes (HEY1, IFNA13, NKX2-3, NR2F1, POU5F1, and YY1)." (PMID 34457116, 2021).
colon cancer (1 paper, 2021). "Previous studies report that IFNA13 may be a potential molecular marker for the prognosis of colon cancer." (PMID 34457116, 2021).
infection (2 papers, 2017 to 2023). The state of being infected such as from the introduction of a foreign agent such as serum, vaccine, antigenic substance or organism. "The RNA levels of many type I IFN genes, including Ifna13, Ifna7, Ifna1/5/6, Ifna1/2/5, Ifna4, Ifnab, Ifna12, and Ifnb1, were significantly increased in IEC4.1 cells 24 h post-infection." (PMID 36928642, 2023).
tumor (2 papers, 2016 to 2021). "The BCPRS-related genes (YY1, POU5F1, NKX2-3, NR2F1, HEY1, and IFNA13) showed high heterogeneity in different cells; thus, the genes can independently predict cellular composition to reflect the microenvironment of tumor tissues." (PMID 34457116, 2021). "In line with this, we found in the TCGA dataset that loss of expression of IFNA13, IFNA21, IFNA6, IFNA8, IFNB1, or IFNW1 was correlated to poor survival, increasing the evidence for the importance of the tumor-stroma microenvironment interaction in gliomagenesis." (PMID 27172220, 2016). "Although genetic changes may affect the level of mRNA expression, the findings of this study showed no significant variation in tumor copy number and nucleotide mutations of the six IMAAG genes (HEY1, IFNA13, NKX2-3, NR2F1, POU5F1, and YY1)." (PMID 34457116, 2021).
cancer (1 paper, 2022). A tumor composed of atypical neoplastic, often pleomorphic cells that invade other tissues. "IL22RA1 was positively correlated with STAT1, STAT3, JAK1, PTPN11, IFNA13, IL24, but negatively correlated with IL10 in specific cancers." (PMID 35874683, 2022).
IFNA13 also shares sentences with these, for which no sentence is quoted: COVID-19 (1 paper); lupus nephritis (1); pancreatic cancer (1).